ZNF420 (zinc finger protein 420)
Description:
May be involved in transcriptional regulation.
Synonyms: FLJ32191; APAK
Tractability: PROTAC: UniProt records ubiquitination sites on it; ubiquitination databases record sites on it.
Gene: Protein-coding gene on chromosome 19 (37,007,823 to 37,130,368, forward strand). Ensembl gene ENSG00000197050.
Subcellular location: Nucleus
Subcellular location (Human Protein Atlas): Nucleoplasm
Pathways (Reactome):
Gene expression (Transcription): Generic Transcription Pathway
Gene Ontology:
Molecular function: protein binding; DNA-binding transcription factor activity, RNA polymerase II-specific; RNA polymerase II cis-regulatory region sequence-specific DNA binding
Biological process: regulation of transcription by RNA polymerase II; regulation of DNA-templated transcription
Cellular component: nucleoplasm; nucleus
Genetic constraint (gnomAD): Loss-of-function variants: 35 observed, 51.95 expected, observed/expected ratio (o/e) 0.67, 90% interval 0.51 to 0.89. The upper end of that interval is the gene's LOEUF score, 0.89, which puts it in group 3 of 6, group 1 being the genes least tolerant of losing a copy. Missense variants: 677 observed, 865.32 expected, observed/expected ratio (o/e) 0.78, 90% interval 0.73 to 0.83. Synonymous variants: 245 observed, 277.52 expected, observed/expected ratio (o/e) 0.88, 90% interval 0.8 to 0.98.
Homologues: Orthologues: macaque ZNF420 (99% identical), rabbit ZNF420 (95% identical), mouse Zfp780b (50% identical), rat Zfp780b-ps1 (49% identical), rat Zfp780b (49% identical), Drosophila melanogaster mld (17% identical), zebrafish zgc:66472 (16% identical). Paralogues in human: ZNF91 (57% identical), ZNF160 (53% identical), ZNF184 (53% identical), ZNF107 (53% identical), ZNF84 (52% identical), ZNF208 (52% identical), ZNF729 (51% identical), ZNF99 (49% identical), ZNF347 (49% identical), ZNF845 (47% identical), ZNF594 (47% identical), ZNF569 (44% identical), and 24 more.
Diseases named in the same sentence as ZNF420 in open-access papers:
ZNF420 is named in the same sentence as 5 diseases in open-access papers, as found by Europe PMC text mining. Sharing a sentence is not in itself a finding about the gene and the disease. The quoted sentences say what the papers report.
colorectal cancer (2 papers, 2016 to 2021). A primary or metastatic malignant neoplasm that affects the colon or rectum. "High expression of ZNF420, also known as APAK, is correlated with a poor prognosis of colorectal cancer patients." (PMID 34638319, 2021).
oropharyngeal cancer (1 paper, 2015). Carcinoma, predominantly squamous cell, arising from the epithelial cells of the oropharynx. "All but ZNF14 are located on the 19q13 locus, which was shown to be epigenetically silenced in oropharyngeal cancer, supporting the hypothesis that ZNF160, ZNF420, ZNF585B, and ZNF71 are epigenetically regulated in a coordinated fashion." (PMID 26544568, 2015).
tumor (4 papers, 2015 to 2021). "Furthermore, DNA methylation changes in selected ZNF genes (ZNF14, ZNF 160, and ZNF420) are detectable in both tumor and saliva of HNSCC patients with high specificity and represent promising biomarkers for the development of non-invasive assays for the detection and surveillance of HNSCC." (PMID 26544568, 2015). "Of all remaining five ZNF protein genes, ZNF14, ZNF160, ZNF71, ZNF420 and ZNF585B, DNA methylation was significantly higher in tumor samples, as compared to normal controls." (PMID 26544568, 2015). "Our data strongly suggest that ZNF420 and ZNF496 are both involved in KIRC progression as tumor suppressors, as their upregulation corresponds to better patient survival and lower tumor grade followed by a significant depletion of cancer stemness characteristics." (PMID 34638319, 2021).
ZNF420 also shares sentences with these, for which no sentence is quoted: cancer (1 paper); sarcopenia (1).